IL33 (interleukin 33)
Diseases named in the same sentence as IL33 in open-access papers (continued):
Sharing a sentence is not in itself a finding about the gene and the disease.
periodontitis (continued). "An association was observed between an IL-33 SNV and 14 ST2 SNVs and periodontitis, suggesting that the different tissue responses among individuals with periodontitis may be influenced by the genetics of the host, altering the expression of genes." (PMID 36947565, 2023). "Since IL-17, IL-6, and IL-33 were found to be significantly elevated in the saliva of SLE/periodontitis subjects compared to periodontitis-only subjects, this systemic imbalance of cytokines may have an impact on periodontal tissues." (PMID 31295952, 2019). "Interestingly, some studies have highlighted a potential role for IL-33 in the regulation of inflammatory process related to RA, a disease sharing many immunopathological similarities with periodontitis." (PMID 27992569, 2016). "We recently discussed a possible role of IL-33 in the pathogenesis of chronic periodontitis." (PMID 27058037, 2016). "We initially analyzed IL-33 expression in gingival tissues from patients with chronic periodontitis by immunohistochemical staining to determine whether inflamed gingival epithelium expresses IL-33." (PMID 27058037, 2016). "Recent studies have demonstrated the involvement of IL-33 in the pathogenesis of periodontitis." (PMID 27403039, 2016). "Recently, it has been suggested that among inflammatory mediators involved in chronic periodontitis (CP), a member of the IL-1 family, IL-33, could play a role in the initiation and the progression of CP." (PMID 27992569, 2016). "The Th2 cytokines IL10 and IL33 remained unaltered in periodontitis patients." (PMID 27531006, 2016). "A third work, which would be similar to the work of Schulze and colleagues, would involve analyzing the effect of the ST2 receptor, the production of proinflammatory cytokines and IL-33, osteoclast formation, and bone erosion in knockout mice with periodontitis." (PMID 24692848, 2014). "In other words, the alteration in circulating ST2 levels in an individual diagnosed with periodontitis could lead to an increase in available IL-33 and, consequently, it could favor bone resorption and contribute to an increase in the severity of periodontitis." (PMID 36947565, 2023). "Thus, reinforcing the hypothesis that these SNVs could have a relevant role in the pathogenesis of periodontitis, through the alteration of the IL-33/ST2 axis." (PMID 36947565, 2023). "How these effects of IL-33 might impact periodontitis remains to be determined." (PMID 34594237, 2021). "IL‐2, ATRA, IL‐33, and chemokine pathways like CCL22 offer promising strategies for enhancing Treg function and restoring immune balance in periodontitis." (PMID 41399014, 2025). "To gain further insight into IL-33/ST2-mediated pathogenesis of periodontitis, we examined cells expressing ST2 and IL-33 in the GT and PRT using flow cytometry." (PMID 38548743, 2024). "Therefore, we induced periodontitis in both Il33Δ/Δ (generated by crossing Il33flox/flox mice with Actb-Cre mice) and Il1rl1–/– mice to determine whether signaling of the IL-33/ST2 axis or its modulation by a soluble decoy contributes to pathogenesis." (PMID 38548743, 2024). "Both IL-33 and IL-1α as alarmins were elevated in GCF and/or plasma in generalized aggressive periodontitis and in chronic periodontitis compared to healthy subjects." (PMID 38098978, 2023). "The pro-inflammatory cytokines IL-6, IL-33 and IL-17A can be proposed as biomarkers of both conditions in GCF due to their ability to trigger the activation of osteoclastogenesis in periodontitis." (PMID 36967976, 2023). "Logistic regression estimated the association measurements, odds ratio (OR), and 95% confidence interval (95%CI), between the IL33 and ST2 genes with periodontitis, and subgroup analyses assessed the relative amount of Aa in these associations." (PMID 36947565, 2023).
periodontitis (continued). "There was a higher prevalence of stage III periodontitis and severe OSA, as well as higher levels of periodontal parameters (PI and BOP), and expression of IL-1β and IL-6 in saliva and IL-6, IL-17A, and IL-33 in GCF, in patients with periodontitis and OSA." (PMID 36967976, 2023). "Periodontitis is an inflammatory disease that mainly has bacterial etiology, where immune cells secreting pro-inflammatory cytokines such as IL-1, TNF, and IL-33, which contribute to tissue damage, are invoked." (PMID 36362030, 2022). "Regarding intestinal tissue analyses, higher levels of IL-1β, IL-4, IL-6, IL-17A, IL17F, IL-21, IL-31, IL-33 and sCD40L were found in patients with IBD and periodontitis." (PMID 34501547, 2021). "High levels of IL-17A, IL-17F IL-22, IL-25, IL-33, IL-10 and INF-y were found in gingival biopsies compared with intestinal biopsies from patients with IBD and periodontitis." (PMID 34501547, 2021). "Regarding intestinal tissue analyses, higher levels of IL-1β, IL-4, IL-6, IL-17A, IL17F, IL-21, IL-31, IL-33 and soluble CD40 ligand (sCD40L) were found in patients having IBD activity and periodontitis." (PMID 34501547, 2021). "A protective role of interleukin-33 (IL-33) against periodontitis has been reported, with another study showing that IL-33 expression levels correlated with nuclear factor-kappa B ligand (RANKL) expression patterns in an animal periodontitis model." (PMID 41374934, 2025). "This sST2 may affect other organs or tissues and induce disease by blocking local IL-33/ST2 signaling, and is likely to play a role in periodontal medicine linking periodontitis and systemic disease." (PMID 38548743, 2024). "Statistically significant adjusted association measurements, odds ratio and 95% confidence interval, between the SNVs of the IL-33 gene and periodontitis, as well as the SNVs of the ST2 gene and periodontitis, considering the severe and moderate severity levels, using dominant genetic model." (PMID 36947565, 2023). "in the oral microbiota of patients with periodontitis and OSA might well be responsible for the high levels of IL-17A and IL-33 in GCF, worsening periodontal disease." (PMID 36967976, 2023). "IL-2, IFN-γ, TNF and IL-33 exhibited an approximately two-fold increase in RA subjects without periodontitis compared to matched controls." (PMID 31182740, 2019). "Nonetheless, it is intriguing that IL-33, but not IL-5 or IL-13, is increased in the WT/periodontitis group but knockdown of AMPK “unleashes” expression of ILCs-2-related cytokines." (PMID 28861078, 2017). "However, the absence of the IL-33/ST2 axis does not affect the bone destruction in periodontitis, suggesting that at least the action of the IL-33/ST2 axis as an alarmin is not critical in the pathogenesis of periodontitis." (PMID 38548743, 2024). "However, some data demonstrated that IL-33 levels in GCF were significantly lower in patients with chronic periodontitis than in patients with gingivitis and patients without periodontal disease." (PMID 36983201, 2023). "Additionally, IL-33 is highly expressed in chronic apical periodontitis lesions with a negative correlation with RANKL and a positive correlation with OPG expression, suggesting a protective role of IL-33 against bone loss in periodontitis." (PMID 36902030, 2023). "Since both IL-33 and TGF-β are known for context-dependent effects, it would be of interest to explore potential cross-talk between them in relation to development and differential regulation of ILCs in periodontitis (and other chronic inflammatory conditions)." (PMID 28861078, 2017). "Although gingival tissues from patients with chronic periodontitis express IL-33, whether or not P. gingivalis increases IL-33 expression in gingival epithelial cells remains unknown." (PMID 27058037, 2016).
periodontitis (continued). "There was a significant positive correlation between stage IV periodontitis and salivary IL-33 (rs = 0.531) in G4 (P-OSA), and there was a significant negative correlation between stage II periodontitis and GCF IL-1β (rs = −0.510, p < 0.05) in G2 (P)." (PMID 36967976, 2023). "Although the cells in the PRT express high levels of sST2, the similar phenotypes observed in both Il33Δ/Δ and Il1rl1–/– mice suggest that accelerated bone destruction is due to the lack of IL-33/ST2 signaling and that its function is protective against local acute inflammation in periodontitis." (PMID 38548743, 2024). "Moreover, concentrations of salivary IL-33 were higher in SLE subjects with PD compared to SLE without PD, which indicates that periodontitis increased the salivary concentration of IL-33 in SLE patients." (PMID 33776578, 2021). "Levels of IL-33 in GCF do not differ between healthy donors and patients with chronic periodontitis and IL-33 is not a component of GCF in inflamed periodontal tissues from patients with chronic periodontitis." (PMID 27058037, 2016).
fibrosis (29 papers, 2018 to 2025). the formation of excess fibrous connective tissue in an organ or tissue in a reparative or reactive process. "We demonstrated that the crosstalk between NET deployments and expression of IL-33, a pro-remodeling mediator was associated with the development of peribronchial fibrosis." (PMID 39877099, 2025). "In HCV-associated fibrosis, serum IL-33 levels correlate with fibrosis stage and viral load, suggesting that IL-33 could be a biomarker for disease progression." (PMID 39995661, 2025). "IL-33 levels are higher in fibrosis and seem to positively correlate with the development and progression of fibrosis and liver damage." (PMID 39201990, 2024). "Previous studies demonstrated that IL-33 is an emerging pro-fibrotic cytokine in SSc fibrosis of lung and skin." (PMID 35877052, 2023). "In this regard, stimulation of lung fibroblasts with recombinant IL-33 induces the secretion of collagen, and mice treated with anti-IL-33 antibodies are resistant to bleomycin-induced fibrosis." (PMID 37240045, 2023). "This shows that both the IL-33–driven lesion proliferation and collagen deposition (by extension fibrosis) are ILC2 mediated." (PMID 34699382, 2021). "IL-33 and IL-13 synergistically induce M2 macrophage polarization, and anti-IL-33 antibody treatment and ST2 deficiency can attenuate bleomycin-mediated pulmonary inflammation and fibrosis." (PMID 33670759, 2021). "In fact, the adherent and invasive E. coli isolate LF82 promotes intestinal fibrosis via IL-33 and ST2 signaling in a Salmonella infection model." (PMID 33431701, 2021). "Our data reveal that the IL-33 pathway leads to shift from acute pulmonary inflammation and remodeling induced by lung damage to an excessive lung repair response with fibrosis through the production of M2-like polarization." (PMID 29988569, 2018). "When mRNA expression of sST2, total ST2, and IL-33 was stratified in these fibrosis categories, a significantly different expression was measured in sST2 (p = 0.012) and IL-33 (p = 0.040)." (PMID 29285671, 2018). "Interestingly, IL-33 administration has ameliorated steatosis but exacerbated certain aspects of steatohepatitis, including fibrosis." (PMID 38248762, 2024). "Additionally, individuals with fibrosis have demonstrated elevated transcript levels of IL-33 in the liver." (PMID 38248762, 2024). "However, prophylactic expansion of Tregs using IL-2c and IL-33 before an injury has a protective effect during kidney injury and fibrosis." (PMID 38343546, 2024). "As a member of the IL-1 superfamily, IL-33 has a pivotal role in sterile inflammation and IL-33/ST2 signaling raises interest in liver pathologies, in particular in alcoholic hepatitis, fibrosis, and LT." (PMID 34621275, 2021). "Here, we revisited the role of the IL-33/ST2 in the BLM model of pulmonary inflammation and fibrosis by both classical immunologic methods and magnetic resonance imaging (MRI)." (PMID 29988569, 2018).
liver disease (29 papers, 2012 to 2026). "Interleukin (IL)-33 is a danger-associated molecular pattern involved in kidney ischemia/reperfusion injury and several liver diseases." (PMID 34621275, 2021). "Our secondary aim is to promote more research in these areas that will assess the diagnostic or therapeutic potential of IL-33 in brain and liver disorders that will ultimately be utilized to inform patient practice." (PMID 32486265, 2020). "It appears that both the NLRP3 inflammasome and the IL-33 pathway can become activated in sterile inflammation-associated liver diseases." (PMID 30213101, 2018). "Recently, much clinical evidence and experimental data have indicated that IL-33 is associated with various liver diseases." (PMID 29180837, 2017). "This section highlights recent advancements in the understanding of the molecular and cellular mechanisms of liver diseases associated with IL-1 family cytokines, particularly focusing on IL-1, IL-33, and IL-18." (PMID 26549942, 2015). "Since IL-1α, IL-1β, IL-33, and IL-36 are implicated in vivo during liver diseases, the efficiency of the therapeutic approaches based on targeting a cytokine by the other members may be affected." (PMID 31507607, 2019). "Based on these findings and the fact that both the NLRP3 inflammasome and IL-33 pathway play a role in the pathology of most of the sterile inflammation-associated liver diseases, it would make sense to study a possible NLRP3-IL-33 axis in sterile liver inflammation in more detail." (PMID 30213101, 2018). "Nevertheless, it is still unclear whether raised IL-33 levels represent the cause or rather a consequence of the progression of HCV-related liver disease." (PMID 23423835, 2012). "Higher concentrations of IL-33 have been found in various liver diseases, such as MASLD, viral hepatitis and cirrhosis." (PMID 40076848, 2025). "Current researches have demonstrated that TNF, IL-1α/β, IL-1Ra, IL-6, IL-18, IL-33, IL-36, IL38, CCL2 and CCR2 are closely associated with liver disorders." (PMID 41333471, 2025). "In liver diseases, IL-33 directly affects innate lymphoid cells as well as hepatic stellate cells (HSCs) that produce collagen." (PMID 40565198, 2025). "In conclusion, endogenous IL-33 can exert opposite effects on liver disease pathology depending on the targeted immune cell populations." (PMID 38571949, 2024). "One possible explanation for this is that the potency of IL-33 is exaggerated during liver disease progression." (PMID 38233853, 2024). "Meanwhile, this study showed the immunomodulatory mechanism of BMSCs after IL-33 pretreatment, which can be expected to further develop MSCs-based therapy for liver diseases." (PMID 39478979, 2024). "Emerging studies have reported that IL-33/ST2 plays a critical role in the process of different liver diseases." (PMID 37081450, 2023). "The role of the IL-1 superfamily in liver diseases can be protective or proinflammatory, and two members, namely, IL-33 and IL-1α, which have been studied the most, are considered bifunctional cytokines." (PMID 35911735, 2022). "Our primary aim is to map the literature on IL-33 in the pathogenesis of brain and liver disorders in order to identify key concepts and uncover plausible gaps in the knowledge." (PMID 32486265, 2020). "Elevated IL-33 levels have been shown in patients with acute and chronic liver inflammation, suggesting that this cytokine plays a role in liver disease pathology." (PMID 31974518, 2020). "In this study, C57BL/6 mice developed fibrosis from a high-fat diet while BALB/c mice did not, demonstrating the importance of strain in drawing conclusions regarding the role of IL-33 in fibrosis and potentially other liver diseases." (PMID 32486265, 2020). "Our results reveal plausible gaps in what is known regarding IL-33 in the pathogenesis of brain and liver disorders." (PMID 32486265, 2020).
liver disease (continued). "Recent studies also describe pro-inflammatory and regulatory roles for IL-33 in the pathogenesis of brain and liver disorders in addition to regulatory roles for this cytokine in the heart and lung." (PMID 32486265, 2020). "This indicated a poor predictive value for plasma IL-33 in assisting the monitoring of liver disease progression in schistosomiasis-diseased school children in our cohort from a polyparasitic area." (PMID 31849991, 2019). "Our group also needs to perform a comparative analysis between EV miR profile and IL-33 specificity and/or sensitivity as an indicator of liver disease in alcohol-intoxicated traumatized patients." (PMID 30859103, 2019). "IL-33, a member of IL-1 cytokines family, has been demonstrated to link to the progression of several liver diseases including acute, acute-to-chronic, and chronic hepatic injury." (PMID 29946260, 2018). "This review summarizes the immunomodulatory roles of the NLRP3 inflammasome and IL-33 in sterile liver inflammation and highlights potential therapeutic strategies targeting these pathways in liver disease." (PMID 30213101, 2018). "Although great progress has been made in understanding the relationship between IL-33 and liver disease, the majority of studies are still based on correlations between IL-33 expression and liver disease." (PMID 29180837, 2017). "The relationship between IL-33 and liver disease, as well as its role in the development of liver disease, has attracted the attention of an increasing number of researchers." (PMID 29180837, 2017). "Interleukin (IL)-33 has been recently reported to be strongly pro-fibrogenic in various models of liver disease." (PMID 28611297, 2017). "Interestingly, serum IL-33 levels were higher in HBV+ versus HBV- patients with other liver diseases, including HCC, cirrhosis, hepatic cyst, fatty liver, and liver hemangioma." (PMID 40579434, 2025). "To assess whether activation of ST2+ Tregs by exogenous IL-33 is critical for the immunosuppressive effect of this cytokine on liver disease pathology, we treated Foxp3Cre x ST2fl/fl mice with IL-33 before induction of hepatitis." (PMID 38571949, 2024). "Serum interleukin-33 (IL-33) levels are correlated with the severity of the liver disease." (PMID 36117587, 2022). "Although the role of some members of the IL-1 cytokine family in liver disease has been extensively studied (IL-1α, IL-1β, IL-33), leading to strong arguments favoring these molecules as potential therapeutic targets, the role of the other members (IL-36, IL-37, IL-38) remains to be elucidated." (PMID 31507607, 2019). "We have tried to apply the concept of trained immunity to liver diseases, based on the role of the members of the IL-1 superfamily, first of all IL-1β but also IL-18 and IL-33, in modulating innate lymphoid immunity carried by natural killer cells, innate lymphoid cells or innate T-αβ lymphocytes." (PMID 31507607, 2019). "Ultimately, this lack of association between plasma IL-33 levels and liver disease was further corroborated by multiple regression analysis (AOR 1.00; 95% CI 0.99–1.01)." (PMID 31849991, 2019). "Thus, targeting IL-33 (e.g., by using an anti-IL-33 antibody) must be well considered and is dependent on the main pathway triggered by IL-33 in a given liver disease." (PMID 30213101, 2018). "Besides, sST2 has been regarded as a circulating biomarker to reflect IL-33 activation and fibrosis in patients with liver diseases." (PMID 30405626, 2018). "There is some evidence that IL-33 is involved in the pathology of liver diseases." (PMID 30213101, 2018). "Further study of IL-33, a novel cytokine, could establish a new field of research on the mechanisms and treatment of liver disease." (PMID 29180837, 2017). "Nevertheless, the role of IL-33 is different in various liver diseases." (PMID 29180837, 2017). "This review primarily addresses the relationship between IL-33 and several hepatic diseases." (PMID 29180837, 2017).